SGK1 (serum/glucocorticoid regulated kinase 1)
Diseases named in the same sentence as SGK1 in open-access papers (continued):
Sharing a sentence is not in itself a finding about the gene and the disease.
edema (2 papers, 2019 to 2023). An abnormal accumulation of fluid beneath the skin, or in one or more cavities of the body. "Thus, SGK1 deficiency increases the severity of hydrops and exacerbates damage to auditory and vestibular function in the LPS-induced EH mouse model." (PMID 36872329, 2023). "In a mouse model of ALI, it was found to stimulate ENaC-mediated AFC through the PPARγ/SGK1 signaling pathway to mitigate pulmonary edema." (PMID 31160894, 2019).
esophageal squamous cell carcinoma (2 papers, 2021). Esophageal squamous cell carcinoma (ESCC) is a type of esophageal carcinoma (EC) that can affect any part of the esophagus, but is usually located in the upper or middle third. "Activation of SGK1 by tongue cancer resistance-related protein 1 induces tamoxifen resistance, and a high expression of SGK1 correlates with a poor prognosis in patients treated with neoadjuvant chemotherapy and esophageal squamous cell carcinoma." (PMID 33406639, 2021). "Targeting TEAD4/YAP1 complex or SGK1 could find application in the treatment of esophageal squamous cell carcinoma." (PMID 33517828, 2021). "Thus, the current study intended to investigate whether SGK1 could act as the downstream target of the TEAD-YAP complex to involve in the progression of esophageal squamous cell carcinoma." (PMID 33517828, 2021).
follicular lymphoma (2 papers, 2021 to 2025). Follicular lymphoma is a form of non-Hodgkin lymphoma characterized by a proliferation of B cells whose nodular structure of follicular architecture is preserved. "Mutations of SGK1 were also detected in DLBCL and follicular lymphoma." (PMID 40613901, 2025). "Of these, mutations in CREBBP, KMT2D, TNFRSF14 and RRAGC were enriched in follicular lymphoma, and those of BTG2, HLA-A, PIM1, IGLL5, SOCS1, CD83 and SGK1 were enriched in DLBCL." (PMID 33945543, 2021). "As expected, mutations in frequent drivers such as CREBBP, KMT2D,TNFRSF14 and RRAGC were more frequent among follicular lymphomas, those of MYC, CCND3 and ID3 prevailed among Burkitt lymphoma and those of BTG2, PIM1, SGK1 and SOCS1 were more frequent among DLBCL." (PMID 33945543, 2021).
head and neck squamous cell carcinoma (2 papers, 2014 to 2025). A squamous cell carcinoma that arises from any of the following anatomic sites: lip and oral cavity, nasal cavity, paranasal sinuses, pharynx, larynx, and salivary glands. "The purpose of this study is to evaluate the therapeutic effect of SGK-1 inhibition in head and neck squamous cell carcinoma (SCC)." (PMID 25485633, 2014). "In order to investigate whether SGK-1 inhibition attenuates the growth of head and neck squamous cell carcinoma cells, we initially treated incubated cell lines HTB41 and HTB43 for 72 hours with SGK-1 Inhibitor, and subsequently compared them to controls." (PMID 25485633, 2014).
kidney cancer (2 papers, 2020 to 2021). Primary or metastatic malignant neoplasm involving the kidney. "A study on A498 kidney cancer cells found that survival signals promoted by IL-2 are mediated by SGK1 activation." (PMID 34249670, 2021). "SGK1 was also demonstrated to be a downstream effector of interleukin-2 (IL-2) in kidney cancer." (PMID 33542904, 2020).
long QT syndrome (2 papers, 2017 to 2023). "Here we show that SGK1 directly regulates NaV1.5 channel function, and genetic inhibition of SGK1 in a zebrafish model of inherited long QT syndrome rescues the long QT phenotype." (PMID 28336914, 2017). "▪Therapeutically inhibiting SGK1 with our novel SGK1 inhibitor effectively shortens the action potential duration (the cellular surrogate for the QT interval) in human iPSC-CM models of all 3 major long QT syndrome genotypes." (PMID 37124559, 2023).
lung diseases (2 papers, 2022 to 2024). "At the beginning, we wanted to clarified the clinicopathological and prognostic significance of SGK1 in lung diseases." (PMID 38250161, 2024).
lymphoma (2 papers, 2020 to 2022). A malignant (clonal) proliferation of B- lymphocytes or T- lymphocytes which involves the lymph nodes, bone marrow and/or extranodal sites. "In DLBCL, mutation of SGK1 may lead to its loss of function, rendering lymphoma cells more sensitive to glucocorticoids, chemotherapy drugs, and radiotherapy, thereby improving prognosis." (PMID 35106936, 2022).
oral squamous cell carcinoma (2 papers, 2020 to 2021). "Since pSGK-1 is the active and the pro-survival form of SGK-1, its reduction in human oral squamous cell carcinoma is suggestive of an adaptive mechanism to curtail tumor growth, an aspect of relevance in relation to the use of SGK-1 inhibitors as a therapeutic option in cancer." (PMID 35048019, 2021).
psoriasis (2 papers, 2025). An autoimmune condition characterized by red, well-delineated plaques with silvery scales that are usually on the extensor surfaces and scalp. "Psoriatic HaCaTs deliver AGAP2-AS1 to CD4+ T cells via exosomes, inducing Th1 and Th17 differentiation through the miR-424-5p/SGK1 axis, thereby promoting the progression of psoriasis." (PMID 40520230, 2025). "Their downstream effector Sgk1 has also been reported to exert anti-inflammatory effects in the imiquimod-induced mouse model of psoriasis." (PMID 40943265, 2025).
renal carcinoma (2 papers, 2021 to 2022). A carcinoma arising from the epithelium of the renal parenchyma or the renal pelvis. "Moreover, SGK1 activation is deciphered to have a pivotal role in controlling the growth of renal cancer cells via IL-2 mediation." (PMID 36266728, 2022).
squamous cell lung carcinoma (2 papers, 2012 to 2020). A carcinoma arising from squamous bronchial epithelial cells. "Expression level of SGK1 was higher in squamous cell lung cancer and correlated with high grade tumors, tumors size and clinical stage." (PMID 32998690, 2020).
thyroid cancer (2 papers, 2020 to 2022). "In vivo preclinical studies have also shown that SGK1 KD in PC-3 xenografts significantly reduces tumor burden and metastatic potential compared to controls, and combining SGK and AKT inhibitors (e.g., 14h and MK-2206) is synergistic in both breast and thyroid cancer models." (PMID 33105713, 2020).
tongue cancer (2 papers, 2015 to 2023). A malignant neoplasm affecting the tongue. "SGK-1 activation and expression can favor the invasiveness and metastasis of human tumors, including tongue cancer." (PMID 38137013, 2023). "We performed in situ hybridizations (ISH) to detect miR-491-3p and immunohistochemical staining to examine Rictor, p-Akt(Ser473), p-SGK1(Ser422) and p-FOXO1(Thr24) in the tissues from 84 tongue cancer patients who received chemotherapy based on PYM and/or cDDP." (PMID 25749387, 2015).
abortion (1 paper, 2023). the ending of pregnancy by removing a fetus or embryo before it can survive outside the uterus. "Our previous results also showed less expression of decidual SGK1 at the maternal–fetal interface of women suffering from early spontaneous abortion." (PMID 37226177, 2023).
adenomyosis (1 paper, 2025). The growth of endometrial tissue inside the muscular wall of the uterine corpus. "Our transcriptomic analysis identified TNFAIP6, matrix metalloproteinase 7 (MMP7), TNFAIP3, leukemia inhibitory factor (LIF), and serum and glucocorticoid-regulated kinase 1 (SGK1) as the top 5 genes implicated in the inflammatory mechanisms of adenomyosis." (PMID 40989079, 2025). "Additionally, LIF and SGK1, known for their roles in implantation and immune modulation, may offer insights into fertility outcomes in adenomyosis patients." (PMID 40989079, 2025).
ankylosing spondylitis (1 paper, 2024). An autoimmune chronic inflammatory disorder characterized by inflammation in the vertebral joints of the spine and sacroiliac joints. "In addition, YXB may also regulate the circadian rhythm expression of Sgk1, thereby It can improve the aggravation of pain at night in diseases such as ankylosing spondylitis, cervical spondylosis, and LDH, but this conjecture still needs further research to be verified." (PMID 39355777, 2024).
Aortic dissection (1 paper, 2025). Aortic dissection refers to a tear in the intimal layer of the aorta causing a separation between the intima and the medial layers of the aorta. "LINC01605 is upregulated in a mouse model of aortic dissection and participates in the cellular processes of migration, proliferation and autophagy associated with aortic dissection by modulating the expression of genes such as SGK1, MMP‐2, MMP‐9, α‐SMA, SM22α, LC3B and p62." (PMID 41294029, 2025). "SGK1 was overexpressed in VSMCs derived from patients with aortic dissection." (PMID 41294029, 2025). "Moreover, SGK1 was overexpressed in the aortic wall tissues and VSMCs of patients with aortic dissection." (PMID 41294029, 2025).
astrocytomas (1 paper, 2016). "In the present paper, we show for the first time that an increased SGK1 mRNA expression was significantly enhanced in high-grade astrocytoma and GBM from well-staged patients, when compared with normal brain tissue." (PMID 26908461, 2016). "In several deposited Geoprofiles datasets, SGK1 expression correlates with grading in astrocytomas, including GBM, the highest grade." (PMID 26908461, 2016).
Cachexia (1 paper, 2022). Severe weight loss, wasting of muscle, loss of appetite, and general debility related to a chronic disease. "In our cachexia mouse model, several of the DE genes enriched in the bulk analysis belong to the top-induced genes in oligodendrocytes, such as Mt1, Sgk1, Klf13, and Ptgds, indicating an important role for oligodendrocytes in the pathology of cachexia." (PMID 35031523, 2022).
cerebral infarct (1 paper, 2023). "The results of a previous study showed that the use of SGK1 inhibitors, including GSK650394 and EMD638683, significantly reduced the size of the cerebral infarct, with GSK650394 providing greater improvement in infarct area." (PMID 36865044, 2023).
cholangiocarcinoma (1 paper, 2020). A carcinoma that arises from the intrahepatic biliary tree (intrahepatic cholangiocarcinoma) or from the junction, or adjacent to the junction, of the right and left hepatic ducts (hilar cholangiocarcinoma). "Additionally, SGK-1 may promote the survival of cholangiocarcinoma cells by mediating the IL-6-related pathway." (PMID 33083492, 2020).
colorectal tumours (1 paper, 2010). "As hyper-methylation of promoter regions is a well known mechanism of gene inactivation and suppression of gene expression, we investigated whether it was responsible for the lowered expression of SGK1 in colorectal tumours." (PMID 21079778, 2010).
congenital long QT syndrome (1 paper, 2023). "▪As a result of this preclinical data, clinical trials with a novel SGK1 inhibitor in patients with congenital long QT syndrome are anticipated to begin enrolling patients later this year." (PMID 37124559, 2023).
cystic fibrosis (1 paper, 2017). Autosomal recessive disorder caused by pathogenic variants in the CFTR gene (cystic fibrosis transmembrane conductance regulator), which encodes a chloride and bicarbonate channel expressed in epithelial cells, and follow the diagnosis criteria. "Moreover, in the transformed cystic fibrosis bronchial epithelial cell line CFBE41o-, the GC-induced increase of serum and GC dependent kinase 1 (SGK1) protein abundance enhanced ΔF508-CFTR and wildtype (wt) CFTR membrane expression by inhibiting their endocytic retrieval." (PMID 28825630, 2017).
dementia (1 paper, 2026). Loss of intellectual abilities interfering with an individual's social and occupational functions. "Elevated expression of SGK1 has been found in postmortem AD brains and the P301S human Tau transgenic mouse model of dementia." (PMID 40921794, 2026). "RNA sequencing (RNAseq) of the prefrontal cortex (PFC) of the P301S human Tau transgenic mouse model of dementia has identified Serum and Glucocorticoid-regulated Kinase-1 (Sgk1) as one of the top-ranking upregulated genes." (PMID 40921794, 2026).
dysplasia (1 paper, 2021). A usually neoplastic transformation of the cell, associated with altered architectural tissue patterns. "Benign keratosis specimens, without evidence of dysplasia, and those of mild-moderate and severe dysplasia showed prominent positive cytoplasmic staining and variable nuclear staining throughout the full thickness of the epithelium for SGK-1." (PMID 35048019, 2021).
epithelial dysplasia (1 paper, 2021). "Furthermore, GILZ and SGK-1 play pathogenic roles in a variety of cancers, but their status in potentially malignant (e.g., epithelial dysplasia) or malignant oral lesions remains unknown." (PMID 35048019, 2021).
female infertility (1 paper, 2025). Diminished or absent ability of a female to achieve conception. "Despite successfully identifying the role of SGK1 in female infertility, therapeutic manipulation for human applications presents several challenges and potential side effects." (PMID 40702548, 2025).
Fibroadenoma (1 paper, 2023). A benign tumor of the breast characterized by the presence of stromal and epithelial elements. "We observed that the staining of fibroadenoma was similar to cancer tissue in SGK1 staining, but it was also similar to normal tissue in Bcl-2 staining." (PMID 37370761, 2023).
fibroid (1 paper, 2023). "The involvement of many proteins, such as LHFPL3, SGK1, and RhoA, shown in the protein-protein interaction network, is well established in fibroid pathogenesis." (PMID 37686244, 2023).
Graves disease (1 paper, 2025). Graves' disease is an autoimmune disorder that leads to overactivity of the thyroid gland (hyperthyroidism).It is caused by an abnormal immune system response that causes the thyroid gland to produce too much thyroid hormones. "XIST, PPP1R2C, CALHM6, AL672277.1, TSIX, SHROOM1, ADTRP, JUND, SGK1, CHKA, AO008569.1, MAP7D2, and AIF1 were down-expressed genes in TS compared with both the healthy female and the female patient with Graves’ disease." (PMID 39851522, 2025).
head and neck cancer (1 paper, 2014). A primary or metastatic malignant neoplasm affecting the head and neck. "Further investigation may be necessary to further elucidate the relationship of SGK-1 and HER 2, and delineate a potential mechanism by which SGK-1 inhibition could reduce HER 2 expression in human head and neck cancer." (PMID 25485633, 2014).
Helicobacter pylori (1 paper, 2016). "Within T cells, Helicobacter pylori (Hp) infection and high-salt dietcan up-regulated SGK1 expression and in turn enhance expression of Lnc-SGK1 through JunB activation." (PMID 26942879, 2016).
hyperthyroidism (1 paper, 2023). Overactivity of the thyroid gland resulting in overproduction of thyroid hormone and increased metabolic rate. "Furthermore, the TSH-increasing allele of SGK1 intronic SNP rs1743963 was associated with decreased risk of both hypothyroidism and hyperthyroidism and in our PheWAS, with increased calcium levels." (PMID 37872160, 2023).
influenza (1 paper, 2013). An acute viral infection of the respiratory tract, occurring in isolated cases, in epidemics, or in pandemics; it is caused by serologically different strains of viruses (influenzaviruses) designated A, B, and C, has a 3-day incubation period, and usually lasts for 3 to 10 days. "SGK3 belongs to the three member family of serum glucocorticoid kinases (SGK1, 2 and 3), and has been shown to regulate influenza vRNP nuclear export into the cytoplasm." (PMID 23805279, 2013).
intestinal tumors (1 paper, 2020). "SGK1 expression also promotes the development of intestinal tumors in adenomatous polyposis coli (APC)-deficient mice, an effect at least partially due to enhanced beta-catenin protein abundance." (PMID 33542904, 2020).
left ventricular hypertrophy (1 paper, 2021). Enlargement of the LEFT VENTRICLE of the heart. "In a mice study, empagliflozin improved SGK1/ENaC profibrotic signaling and associated interstitial fibrosis, as well as left ventricular hypertrophy and left ventricular relaxation, in addition to glycemic indices." (PMID 34281221, 2021).
lupus nephritis (1 paper, 2019). Glomerulonephritis in the context of systemic lupus erythematosus. "Of note, an increase of TH1 cells was reported before in a model of lupus nephritis in an SGK1 dependent manner and possibly could explain the HSD mediated effect on tumor growth." (PMID 31214164, 2019).
male infertility (1 paper, 2011). The inability of the male to effect fertilization of an ovum after a specified period of unprotected intercourse. "Although it is known that testicular torsion leads to testicular damage and male infertility, the role of SGK1 in torsion remains unclear." (PMID 20738430, 2011).
melanoma (1 paper, 2015). A malignant, usually aggressive tumor composed of atypical, neoplastic melanocytes. "Although shRNA knockdown of INPP4B did not impinge on phosphorylation of SGK1, it inhibited SGK3 activation in Mel-RM and ME4405 cells, suggesting that INPP4B preferentially affects SGK3 activation in melanoma cells." (PMID 26573229, 2015).
nephrotic syndrome (1 paper, 2014). A collection of symptoms that include severe edema, proteinuria, and hypoalbuminemia; it is indicative of renal dysfunction. "In the present study, Sgk1 mRNA expression was strongly enhanced in rats with PAN-induced nephrotic syndrome compared with normal rats, but the WPC group had an unaltered Sgk1 mRNA expression compared with that in rats with PAN-induced nephrotic syndrome." (PMID 25165480, 2014).
neuritis (1 paper, 2012). A neuropathy arising from inflammation of one or more nerves. "Also, genes involved in nervous system development were found, for example ATP1B1 (involved in aggregation of neurons), TRIM2 (neuroprotection of cortical neurons) and VAPA, SGK1 and ZFYVE27 (involved in morphogenesis of neuritis)." (PMID 23028713, 2012).
ocular toxoplasmosis (1 paper, 2019). Ocular toxoplasmosis is an infection in the eye caused by the parasite, Toxoplasm a gondii. "In our results—obtained in human retinal Müller cells, which have direct relevance to ocular toxoplasmosis—LINC01105, BANCR, MIR17HG, MIR155HG, lnc-SGK1, MEG3, KCNQ1OT1, NEAT1, NeST, and MALAT1 were the most dysregulated lncRNAs with known immunologic activities." (PMID 31547203, 2019).
osteonecrosis (1 paper, 2025). A none disease characterized by death of bone tissue due to a lack of blood supply. "Given the pivotal role of SGK1 in modulating cellular responses, research on SGK1 in the field of osteonecrosis holds huge promise." (PMID 40881701, 2025).
pancreatic carcinomas (1 paper, 2006). "During a time kinetic from 24 to 72 h, DEX strongly enhanced the levels of MKP-1, SGK1 and X-IAP, in several pancreatic cancer cell lines examined, while Bcl-2 expression was only marginally increased." (PMID 16539710, 2006). "Therefore, enhanced expression of MKP-1, SGK-1, X-IAP and Bcl-2 but not of BAG-1 may be involved in DEX-induced therapy resistance of pancreatic carcinomas." (PMID 16539710, 2006).